CD4 (CD4 molecule)
Diseases named in the same sentence as CD4 in open-access papers (continued):
Sharing a sentence is not in itself a finding about the gene and the disease.
infection (continued). "WT or Ezh2–/– Smarta CD4+ T cells were adoptively transferred into congenic recipients, followed by LCMV-Arm infection." (PMID 30575739, 2018). "Since Mtb downregulates Ag85b expression by 3 weeks post infection, we used an ESAT-6-specific CD4+ T cell line derived from C7 transgenic mice, which we refer to as C7 T cells." (PMID 29782535, 2018). "After 6 wpi, CD4+ T cell counts in stHIV-1sv infected NPMs presented a modest fluctuation, different from that of HIV-1NL4−R3A infection." (PMID 30210504, 2018). "Resting CD4+ T cells were first co-cultured with LEC and then infected just as in productive infection experiments." (PMID 30285810, 2018). "A 1:1 mix of naive CD4+ T-cells from Lmna−/−/OTII and WT/OTII mice was adoptively transferred into WT recipient mice before intradermal infection with VACV-OVA." (PMID 29311549, 2018). "On day 6 of infection, however, we observed an increased percentage of ICOS-positive CD4+ and CD8+ T cells as compared to uninfected mice." (PMID 29892278, 2018). "We furthermore analyzed the presence of B. bronchiseptica-specific CD4+CD25+Foxp3+ Treg in infected mice, six weeks following the infection." (PMID 30200513, 2018). "CD4+/CD8+ T cell ratio, which had dropped significantly during acute EBV infection, also recovered once infection was cleared." (PMID 29472930, 2018). "We showed that ST2−/− mice had higher number of gated CD4+IFN-γ+T cells than WT mice at days 7 and 14 post-infection." (PMID 29867945, 2018). "We further evaluated the post-infection CD8+ and CD4+ T cell responses in the EVD survivors and the seropositive EVD contacts." (PMID 29795572, 2018). "Peripheral CD4, CD8, and CD21 cells progressively and markedly declined during the asymptomatic stage of infection (respectively)." (PMID 29794987, 2018). "Peripheral T cells in scrub typhus patient blood have been characterized recently, where the percentage of both CD4+ and CD8+ T cells decreased due to programmed cell death (apoptosis) during the acute phase of infection." (PMID 29760694, 2018). "Last, we compared the virus clones to JR-FL and JR-CSF in infection assays of Affinofile cells expressing high levels of CCR5 and increasing amounts of CD4, as previously reported." (PMID 30521629, 2018). "Consistent with its potency, F-MLV-NB envL128I infection primed Vα2+ as well as Vα3+ env-reactive CD4+ T cell clonotypes, in contrast to WT F-MLV infection, which favored Vα2+ clonotypes." (PMID 29951052, 2018). "In particular, we found direct correlations of Env-specific CD4+ T cells with NAb against SIVsmE660-CG7G and SIVsmE660/2A5-VTRN, NAb responses which were also found to be correlates of a delay in infection." (PMID 29793957, 2018). "In fact, low viral fusion, infection, and replication activities were not the consequence of a lower cell surface expression of the Envs, the levels of which were similar in both groups, but were linked to a lower ability to bind to CD4 in a cell-to-cell HIV-1 transfer assay." (PMID 29636433, 2018). "Infection with IAV elicits a vigorous adaptive immune response that involves virus-specific CD8+ cytotoxic T lymphocytes (CTL), conventional and regulatory CD4+ T cells, and virus-specific antibodies." (PMID 29379138, 2018). "While the CD4, CCR5, CXCR4 axis for cell-free infection has been the most studied, there are a plethora of reports suggesting that the cell-to-cell transmission of HIV-1 is significantly more efficient." (PMID 30619107, 2018). "Immune competence of HIV-infected animals was also indicated by stable CD4+:CD8+ cell ratios at 1 and 4 months after infection and induction of adaptive immune responses when infected mice were challenged with an unrelated antigen." (PMID 29879225, 2018). "(C) Virus-specific CD4 +T cells and CD69 expression on CD4 +T cells in peripheral blood at early time points post-infection (p.i.)(n = 7–8 mice per genotype)." (PMID 29848443, 2018).
infection (continued). "Based on previous studies and the data presented here, we propose the following model of liver dysfunction during HIV/SIV infection that is initiated by infection of SIV target cells, presumably CD4 T cells, that localize around portal triads." (PMID 29466439, 2018). "A cell-mediated immune response involving both CD4 and CD8 T cells is generally important for controlling infection by intracellular pathogens." (PMID 30631322, 2018). "Accordingly, combined CD4+ and CD8+ T cell depletion also prevented the so-called “late resolver” phenotype (wherein some mice resolve their CFT073 infection between days 21 and 28 post infection)." (PMID 30543708, 2018). "The importance of HCV-specific CD4+ and CD8+ T cell responses in the clearance of primary infection and reinfection has been reported." (PMID 30096846, 2018). "Approximately one in 105 to 108 CD4+ T cells is latently infected in most patients, with the rate of infection depending on individual variability and when ART was started after infection." (PMID 30316868, 2018). "Particularly, cellular immunity, including CD4 and CD8 T cells specific to O. tsutsugamushi antigens, quickly decline from 1 year after infection." (PMID 30233599, 2018). "CD4 and CD8 TRM cells can be induced following infection at mucosal sites or the skin, where they are maintained and poised to respond rapidly to reinfection with the same pathogen." (PMID 30147701, 2018). "Infection with T. gondii provides a strong stimulus for antigen-specific CD4+ and CD8+ T cells, which suggests that the parasite antigens are efficiently acquired by APCs and presented to antigen-specific T lymphocytes during infection." (PMID 29459857, 2018). "Several immune mechanisms, involving CD4+, CD8+, and γδ T cells, have been shown to contribute to the control of Mtb after an infection has been established." (PMID 29520269, 2018). "Taken together, these studies strongly suggest that ICOS plays a critical role in CD4+ and CD8+ T cell response in both intra and extracellular infection." (PMID 29892278, 2018). "Hence, incidental recruitment of CD4+ T cells to sites of HIV entry (female reproductive tract and rectum) by prime and pull vaccination strategies may unintentionally increase susceptibility to infection." (PMID 30038624, 2018). "To achieve infection of both CXCR4 and CCR5 HIV-1 strains, we utilized a HuT78 cell line, which expresses an endogenous level of CD4 and CXCR4 but was transiently transduced to express CCR5 and different IFITMs." (PMID 30087232, 2018). "That is, increased CD32 expression after infection of CD4+ resting T cells with a modified HIV-1 circumvents SAMHD1-induced restriction allowing productive infection." (PMID 30013105, 2018). "We next transduced WT CD45.2+ Smarta CD4+ T cells with a bicistronic pMSCV-IRES-GFP retrovirus expressing WT or mutant p19Arf protein, followed by adoptive transfer and LCMV-Arm infection." (PMID 30575739, 2018). "The PD1/PDL1 blockade has been found to restore both CD4+ and CD8+ T cells function, especially in terms of high IFNγ and low IL-10 production, in L. infantum and L. major infections." (PMID 29915577, 2018). "We examined the frequency and number of activated Tfh cells (CD4+CD62L−CXCR5hiPD-1hi) in the spleens of mice at days 6 and 15 after infection with PbAWT or PbAmif− parasites." (PMID 30006528, 2018). "Taken together, our data clearly demonstrated the development and maturation of both CD4+ and CD8+ PFC from early to long term infection stages in IM patients." (PMID 29599759, 2018). "The frequencies of the T cell memory populations CD45R0+CD3+CD4+ and CD45R0+CD3+CD8+ were higher at 30 DPI than on the day of infection." (PMID 29522489, 2018). "IFN-γ is also important for orchestrating the ongoing adaptive immunity, contributing to differentiation of CD4+ Th1 and CD8+ T cells, required for the control of the parasite multiplication occurring during the acute infection." (PMID 29774028, 2018).
infection (continued). "However, although directly not measured in this study, induction of IgG2a by these immunogens might be a demonstration of active helper T lymphocyte expansions through targeting CD4 + T cells, which are crucial for development of memory cells and long-term protection against infection." (PMID 29854852, 2018). "In contrast, infection with virulent wild-type Leishmania donovani parasites resulted in a strong induction of CD200–CD200R immune inhibitory signals in both DCs and the CD4+ T cells." (PMID 29915577, 2018). "At three weeks post-infection with L. major, the number of IFN-γ-producing, and to a lesser extent IL-10-producing, TCRß+CD4+ splenic T cells was higher in mice coinfected with T. b." (PMID 30619253, 2018). "All the selected mice for infection and uninfected groups efficiently developed a human immune system, as shown by the presence of human CD45+ cells (62±4%), and T cells including CD4+ (mean±s.e.m." (PMID 29361613, 2018). "In 5 additional HIV-infected normal donor cervical explants, we used qRT-PCR to amplify HIV RNA from sorted cervical CD3+CD4+ T cells, CD14+CD11c+ DCs, and CD14+CD11c- macrophages harvested 20 h post-infection." (PMID 30532754, 2018). "We observed that infection with the fbp1Δ mutant induced enhanced differentiation of IFN-γ-secreting Th1 cells and IL-17A-secreting Th17 CD4+ T cells." (PMID 29317510, 2018). "CD4 T cell-mediated help to CD8 T cells and B cells is a critical arm of the adaptive immune system required for control of pathogen infection." (PMID 29734372, 2018). "In correlation with the cytokine secretion to supernatants by splenocytes, the intracellular expression of cytokines by CD4+ T lymphocytes in response to NH36, was more intense on day 15 than on day 28 after infection." (PMID 29867949, 2018). "Using adoptive transfer of CTV-labeled Blimp1-YFP+ Smarta CD4+ T cells followed by LCMV infection, we distinguished Blimp1-YFPhi nascent TH1 and Blimp1-YFPlo nascent TFH cells, at the 5th division at 60 h post-infection." (PMID 30575739, 2018). "MΦ were loaded with a low multiplicity of infection (MOI) of HIV-1 R5-tropic BaL (MOI, 10−3), followed by coculture with autologous CD4+ T cells and assessment of HIV-1 p24 core antigen in cell-free supernatant." (PMID 29643243, 2018). "CD4+ cells are important during the acute phase of infection, whereas CD8+ has a role in clearance of infection during the chronic phase of infection." (PMID 29362230, 2018). "In contrast to MHC class I, MHC class II epitopes are presented efficiently upon infection with CVB3 and CD4+ T cells mature quickly into effector and later on into memory T cells." (PMID 30546359, 2018). "Depending on the nature of antigen and chronicity of infection, ICOS signaling mediates differential effector CD4+ T cell response." (PMID 29892278, 2018). "HIV-1 has evolved multiple means of downregulating CD28, which are in part genetically separable from CD4 and MHC-I downregulation, implying that CD28 downregulation is critical during infection." (PMID 29329537, 2018). "In future studies, we plan to decipher the role of Th1 responses at the primary site of infection (mucosal site) and to validate that CT-specific IFN-γ-producing CD4+ T cells traffic to mucosa and are directly involved in providing protection." (PMID 30245688, 2018). "Our analysis demonstrates that specific LILRA2+ CD64+ CD32a+ CD4+ T-cell clusters, characterized by naive and memory T-cell phenotypes, were more abundant in HIV+ patients from the early phase of infection." (PMID 29915583, 2018). "Three days after infection, HIV infectivity in vector-specific CD4 T cells was measured by flow cytometry based on intracellular HIV p24 expression in CFSE-low CD4 T cells." (PMID 29474461, 2018). "Eosinophils from a rat model of cryptococcosis have also been demonstrated to have the ability to phagocytose cryptococci and prime of CD4+ and CD8+ T-cells, in vitro although their role in human infections is less clear." (PMID 29670625, 2018).
infection (continued). "In this regard, lymph nodes (LN) memory Tfh cells and to a lesser extent memory CXCR5−PD-1+ CD4 T cells were previously shown to serve as the major CD4 T-cell compartments for HIV replication, production and infection in viremic HIV-1-infected individuals." (PMID 29459864, 2018). "The frequency of CD4+ cells was similar between infected CCR4−/− and WT groups at 15, 30 and 70 days of infection." (PMID 30584243, 2018). "Compared to LdWT infection, the percentage of CD200+ DCs and CD200R+ CD4 T cells was found significantly less in LdCen−/−-immunized animals." (PMID 29915577, 2018). "Protection against infection with SIV correlates with the induction of ADCC-promoting antibodies specific to the CD4-T-cell epitopes and occurs on the background of a balanced CD4+ T-cell response." (PMID 29799015, 2018). "In the context of HCV-infection, however, the differentiation fate of HCV-specific CD4 T cells is less precisely defined." (PMID 30453612, 2018). "Lung infiltrating leukocytes from DT-treated and untreated DEREG mice were obtained at weeks 6 and 10 after infection and intracellular presence of IFN-γ+, IL-4+ and IL-17+ in CD4+ and CD8+ T cells was assessed by flow cytometry." (PMID 30410119, 2018). "Additional experiments are required to demonstrate which of the CD4+, CD8+ T cell and/or antibody responses after vaccination/infection are responsible for protection." (PMID 30011277, 2018). "When disease, inflammation or infection is present, CD69+ activation increases on CD4+ and CD8+ cells, and is used as an early indicator of T-cell activation." (PMID 30126153, 2018). "A significant increase in mean fluorescent intensity for ICOS on CD4+ and CD8+ T cells suggested that expression of ICOS at protein level per cell was also higher on day 6 of PbA infection." (PMID 29892278, 2018). "On day 3 and day 6 of PbA infection, mice were sacrificed and their spleens analyzed for surface markers to identify ICOS expression on CD4+, CD8+, NK, NKT, and B cells by flow cytometry." (PMID 29892278, 2018). "To analyze the capacity of both CD4+ and CD8+ T cells to eliminate the bacteria in vivo we further determined the bacterial load in different organs of all groups of mice on day 7 post infection by qPCR." (PMID 28222146, 2017). "Our results revealed that splenocytes from mice immunized with OVA-loaded DCs in the presence of DenV2 infection proliferated in response to stimulation with OVA protein (left), which has been known to induce the dominant proliferation of CD4+ Th cells." (PMID 29285314, 2017). "If the percentage of CD4+ T cells, CD4+/CD8+ ratio, and IgG concentration are low, the physician should consider the possibility of infection." (PMID 29267496, 2017). "The role of CD4+ and CD8+ T-cell and antibody responses, particularly against blood-stage infection, remains elusive mostly due to the diversity of experimental protocols, the biology of the Plasmodium strains used, and host genetics." (PMID 28831137, 2017). "We observed an overall trend toward increased total numbers of CD4+ and CD8+ T cells in H99γ immunized mice compared to HKH99γ immunized mice following challenge with each serotype as the infection progressed." (PMID 29163469, 2017). "In CD4-depleted, HIV+ individuals with AIDS, infection of the brain and other macrophage rich tissues contributes to late stage pathology and morbidity." (PMID 28752134, 2017). "When cells were exposed to EBOV at a multiplicity of infection (MOI) of 1 PFU/cell, a shift in the bulk population of cells and the development of an EBOV glycoprotein (GP)Hi population were detected in both CD4+ T cells (13.3%) and Jurkat cells (12.7%)." (PMID 28951472, 2017). "Moreover, because the bone marrow ASCs and IgM memory cells differ in their requirement for CD4 T cell help, we suggest that B cell fate is determined by the availability of signals from Tfh cells that are also present in abundance in the spleen during infection." (PMID 28575114, 2017).
infection (continued). "This difference in early chemokine production is consistent with our findings that CD4+ T cells, CD8+ T cells, and NK cells are less efficiently recruited during Opal524R infection." (PMID 29138302, 2017). "As lymphocytes are necessary for effective clearance of C. neoformans, we compared the recruitment of CD4+ or CD8+ T cells, γδT cells, and B cells to the lungs of WT and IL-1RI−/− mice at different time points after infection." (PMID 29403476, 2017). "Despite large numbers of IFN-γ producing CD4+ T cells in the skin, monocytes and monocyte derived cells had lower levels of MHCII expression at the population level during secondary infection compared to primary infection." (PMID 28666021, 2017). "Before infection, old ChRM had a significantly lower number of CD4+ T cells (869.9 cells/μl) and a higher frequency of CCR5+CD95+CD4+ memory T cells (18.60%) than did young macaques (1069.0 cells/μl and 10.09%, respectively; P = 0.02 and 0.008, respectively)." (PMID 28232735, 2017). "Experimental evidence suggests that 2B4 levels were elevated on CD4, CD8, and NK cells during chronic HCV and HIV infections." (PMID 28396665, 2017). "After primary infection but prior to secondary rechallenge, C57BL/6 mice were depleted of neutrophils (alone or in combination with CD4+ T cells) via anti-Ly6G administration." (PMID 28739831, 2017). "Among 2.2% (n =21/949) of cases defined as late presenters by CD4 cell count or CDC stage, a recent infection was identified by using the BED-CEIA." (PMID 28693564, 2017). "To test for this, we first plotted the infection rates of CD2+ PBMC, CD2+ CD3+ T cells and CD2+ CD4+ cells of HIV-1 patients controlling the infection or showing a progressive course of infection." (PMID 28953327, 2017). "A small number of non-transgenic WT CD4+ T cells were detected in the retina on day 7 post-infection, while few if any HEL-specific CD4+ donor T cells were present." (PMID 29079770, 2017). "48h post-infection, we detected a significant increase in the concentration of IFN-γ in the co-cultures with blood derived CD4+ T-cells where LAG-3 expression was silenced relative to those where silencing was not performed." (PMID 28880895, 2017). "Previously, we showed that human BBB pericytes express the major HIV receptor CD4 and co-receptors CXCR4 and CCR5, which results in their infection by HIV and compromises BBB integrity via functional alterations of endothelial cell tight junction proteins." (PMID 29311803, 2017). "At the beginning of infection, HIV infects immunocytes such as dendritic cells, macrophages and CD4+ T cells in the human intestinal mucosal." (PMID 29163506, 2017). "In otherwise immunocompetent BALB/c mice, IFNγ neutralization increased d9 lung virus titers significantly more than did CD4+ T cell depletion, and increased both AM and AEC1 infections, implying that it also mediated other anti-viral effects." (PMID 28394921, 2017). "Also, high systemic CXCL10 levels before infection were revealed to be associated with rapid HIV progression, and the level of systemic CXCL10 during primary HIV infection is positively associated with HIV DNA levels and viral load and negatively associated with CD4+ T cell count." (PMID 29085362, 2017). "Peripheral blood samples from patients with ALF had a higher proportion of CD4+ CTLA4+ T cells than controls; patients with infections had the highest proportions." (PMID 28363639, 2017). "Virus-specific CD4+ (Th1) and CD8+ (Tc1) T cells were sources of IFN-γ early in infection, while CD8+ T cells were the predominant sources of IFN-γ later in infection." (PMID 28904342, 2017). "At days 3, 7, and 10 post infection (p.i.), the phenotype of gated CD8+ and CD4+ T cells was analyzed by flow cytometry." (PMID 29085373, 2017). "The AAV-transduced CD4+ T cells were infected with HIV-1NL4-3 and the culture supernatants were collected at 1–5 days post-infection for p24 detection." (PMID 29141633, 2017).